RNVU1-32 (RNA, variant U1 small nuclear 32)
Synonyms: U1A4; RNU1-106P
Gene: Small nuclear RNA gene on chromosome 8 (127,999,131 to 127,999,294, forward strand). Ensembl gene ENSG00000207110.
Gene Ontology:
Molecular function: pre-mRNA 5'-splice site binding
Biological process: mRNA 5'-splice site recognition
Cellular component: U1 snRNP
Homologues: Orthologues: chimpanzee U1 (98% identical), macaque U1 (88% identical), mouse Gm23330 (88% identical). Paralogues in human: RNU1-1 (91% identical), RNU1-2 (91% identical), RNU1-27P (91% identical), RNU1-28P (91% identical), RNU1-3 (91% identical), RNU1-4 (91% identical), RNU1-89P (91% identical), RNVU1-18 (91% identical), RNVU1-29 (91% identical), RNVU1-31 (91% identical), U1 (91% identical), RNVU1-28 (91% identical), and 134 more.